STAT1 (signal transducer and activator of transcription 1)
Diseases named in the same sentence as STAT1 in open-access papers (continued):
Sharing a sentence is not in itself a finding about the gene and the disease.
cancer (741 papers, 2002 to 2026). A tumor composed of atypical neoplastic, often pleomorphic cells that invade other tissues. "Our data indicate that P4HA2 increases the expression of PD-L1 by binding to and downregulating STAT1 expression, thereby increasing the risk of cancer." (PMID 40406250, 2025). "Previous studies have shown that high STAT1 expression is associated with improved survival and a protective role in cancer progression, which aligned with our findings." (PMID 40599331, 2025). "RNase1 enables cancer cells to prevent CD8+ T‐cell attacks through signal transducer and activator of transcription 1 (STAT1) inactivation, causing T‐cell dysfunction and underscoring RNase1's immunosuppressive role." (PMID 39932384, 2025). "Mice expressing functionally inactive STAT1 display increased susceptibility to microbial infections and develop a variety of murine cancer entities." (PMID 40287766, 2025). "Three of these four genes, BRCA1, PSMD4, and RPL3, are reported as cancer genes, and STAT1 is associated with both cancer and AIDs." (PMID 40429780, 2025). "In A549 cancer cells, the conditioned medium from NK-92 cells caused the phosphorylation of STAT1 at Tyr701, as well as the upregulation of the IRF1 and CASP1 proteins, which is consistent with the activity of IFNγ." (PMID 40512405, 2025). "Aberrant STAT1 expression has been linked to cancer biology, serving as both a prognostic marker and a target for cancer therapy." (PMID 41367865, 2025). "In fact, the authors found that VitC treatment of human and mouse cancer cell lines induced vitcylation of a specific lysine residue (K298) in STAT1 associated with enhanced phosphorylation at tyrosine 701 and increased STAT1 activity." (PMID 40583064, 2025). "To explore the mechanisms underlying this inhibitory effect of P4HA2 on STAT1, we investigated signaling pathways significantly associated with cancer via STAT1." (PMID 40406250, 2025). "STAT1 mainly acts as an inhibitor of cancer as its expression is associated with a better prognosis." (PMID 38611065, 2024). "The epigenetic activity of transcription factor motifs linked to cancer immunogenicity, e.g., Irf1/2/8/9, Stat1, and Nfkb1, were increased in KO cells, which coincided with findings in a PRRX1-overexpressing cell line model." (PMID 39255035, 2024). "The persistent IFN signaling in cancer cells can cause epigenetic changes that enhance open chromatin linked with STAT1 and ISGs." (PMID 38672681, 2024). "While the loss of STAT1 is a common occurrence in tumorigenesis, there are different perspectives regarding its role in cancer immunology." (PMID 38675812, 2024). "Signal transducer and activator of transcription 1 (STAT1) is a cancer associated gene, which is involved in the cytokines (interferon-α/γ and interleukin-6) and growth factor response." (PMID 38227591, 2024). "IKKβ inhibitors (TPCA-1 and Cerdulatinib) abrogated EPS-induced STAT1 phosphorylation and subsequent cancer associated phenotypes." (PMID 38074643, 2023). "A decrease or loss of STAT1 activity has been reported for many cancer types, including tumors with CIN, and high STAT1 expression levels correlate with better clinical outcomes." (PMID 37561163, 2023). "One important risk factor for the increased incidence of cancer is the production of nitrosamines related to Candida, and there is also a role of signal transducer and activator of transcription 1 (STAT1) defects." (PMID 37374978, 2023). "Here, STAT1 signaling in cancer cells with CIN was associated with immune cell attraction and activation, which was decreased upon loss of STAT1." (PMID 37561163, 2023). "As demonstrated in the performed study, different forms of cancers have been linked to the dysregulation of cell cycle genes and STAT1/3." (PMID 36497125, 2022).
cancer (continued). "Higher STAT1 expression has been associated with a different clinical outcome in cancer patients, indicating that patients with a high expression of STAT1 in cancer tissues experience worse clinical outcomes, compared with patients with low expression levels." (PMID 36406891, 2022). "Meanwhile, recent report showed that activation of STAT1 is associated with cancer stemness increase." (PMID 36245000, 2022). "We have found that high level of STAT3 and STAT1 transcripts was associated with poor survival in patients through pan-cancer analysis." (PMID 35874683, 2022). "In tumors, STAT1 is often considered to be a promotor of antitumor activity, but STAT1 induction has also been implicated in cancer progression." (PMID 35515130, 2022). "Consistent with previously conducted studies, this study also demonstrated that exposure to alisertib contributed to cancer cells harboring relative resistance to it, in association with the aberrant expression of STAT1 mRNA and protein levels." (PMID 34522170, 2021). "Recently, Luo and colleagues showed that THC is implicated in the crosstalk between cancer cells and vascular endothelial cells in a Stat1-dependent manner." (PMID 34943903, 2021). "Further study for the molecular mechanism of GBP5-associated EGFR, STAT1, chemotherapy resistance-associated cancer stemness markers, and PIM1 is warranted in OSCC." (PMID 34439200, 2021). "STAT1 is overexpressed in specific cellular environments and is associated with poor prognosis in cancer patients." (PMID 35003395, 2021). "Signal transducer and activator of transcription 1 has been implicated in the pathophysiological processes of several types of cancers and plays dual roles." (PMID 34276757, 2021). "We previously showed that activation of CD95 caused upregulation of IFN-I that activated a STAT1 dependent signaling pathway resulting in increased cancer stemness." (PMID 31992798, 2020). "Previous studies have indicated that STAT1 is an inhibitory factor in the development of several cancers and highly expressed STAT1 is associated with longer OS of patients with OC." (PMID 32516753, 2020). "The upregulation of antiapoptotic and proinflammatory molecules, such as COX2 and iNOS, in response to STAT1 stimulation is frequently linked to tumorigenesis and cancer persistence." (PMID 31842362, 2019). "While STAT1 is often discussed as promoting antitumor activity—the flipside of STAT3-driven protumor signaling—STAT1 induction has also been implicated in cancer progression." (PMID 31842362, 2019). "Previous studies indicated that loss of STAT1 expression has been implicated in the pathobiology of various types of human cancer." (PMID 30641486, 2019). "The failure of cancer cells to respond to IFNy caused by acquired mutations in the IFNy-STAT1 signaling pathway is an important predictor for cancer progression and patient survival." (PMID 31196219, 2019). "Among them, YES and signal transducer and activator of transcription 1 (STAT1), both of which have previously been associated with cancer development, were experimentally verified by qRT-PCR." (PMID 28115926, 2016). "Cancer cells selected for radiation damage resistance were shown to constitutively express select ISGs in a manner associated with STAT1 overexpression." (PMID 27533247, 2016). "Loss of STAT1 (Signal Transducer and Activator of Transcription-1) has been implicated in the pathobiology of a number of cancer types." (PMID 25355139, 2014). "Recently, several studies have indicated that lung cancer associated transcript 1 (LUCAT1) is a cancer-related and myeloid cell-specific lncRNA that can interact with signal transducer and activator of transcription 1 (STAT1) to inhibit the transcription of interferon-stimulated genes." (PMID 40833782, 2025). "Yet as SP100 levels decrease, STAT1 is suppressed, which causes uncontrolled division of cells and may result in traits like cancer." (PMID 41188771, 2025).
cancer (continued). "At present, there are many examples of overexpression and overactivation of STAT1 associated with cancer, and various strategies have been employed to develop STAT inhibitors, including interfering with SH2-mediated dimerization, DNA binding, or deactivation and inducing STAT degradation." (PMID 39539545, 2024). "Therefore, it remains imperative to continue scrutinizing the effects of STAT1 on the progression of HPV-associated cancers." (PMID 38675812, 2024). "However, the mechanisms underlying regulation of STAT1 activity in cancer cells with CIN are still poorly understood." (PMID 37561163, 2023). "Similarly, the association between STAT1 and Cd274 was stronger in cancerous tissues in multiple cancer types." (PMID 37055410, 2023). "As a well-established modulator of cholesterol, it is unclear from these studies whether the anti-cancer activity is associated with STAT1 modulation." (PMID 37173951, 2023). "Interferon signaling associated with STAT1 phosphorylation at tyrosine 701 by JAKs leads to the dimerization of STAT1 and nuclear translocation that regulates interferon-stimulated genes and leads to the appropriate immune surveillance of cancer." (PMID 36980641, 2023). "Mutations in STAT1, -2, -3, -5B, -6, while rare are associated with multiple inherited conditions, particularly primary immunodeficiencies, autoimmune diseases and even cancers." (PMID 35844493, 2022). "Due to limited GC samples in our proteomic cohort to establish associations, we referred to The Cancer Genome Atlas Stomach Adenocarcinoma (TCGA-STAD) database to analyze the expression of STAT1 and PD-L1 and their correlation with immune infiltration based on mRNA level." (PMID 35456965, 2022). "Aberrant activities of STAT1 have been implicated in cancer development." (PMID 35440542, 2022). "STAT1-dependant IFN signaling has been shown to induce stemness in cancer cells, that might contribute to p190-associated phenotype." (PMID 33168949, 2021). "Moreover, Stat1 overexpression is associated with the protection of cancer cells from radiation and chemotherapy." (PMID 34685622, 2021). "Moreover, activation of STAT1 has been predicted to also upregulate expression of cancer associated genes such as IDO1 and PTGS2." (PMID 34946170, 2021). "For example, it is known that STAT4/STAT1 can form heterodimers in response to IL-35, an immunosuppressive cytokine associated with the generation of Tregs and with poor prognosis in some types of cancer." (PMID 33076315, 2020). "We speculated that upregulations of p-Stat1 in ESCC cancer cells may cause an increase of proteasomal degradation of cyclin D1, resulted in the less dramatic upregulations of protein levels of cyclin D1 in human ESCC tissue samples." (PMID 33046973, 2020). "In recent years, IFNγ/STAT1 pathway has been linked to metastatic progression of cancers." (PMID 31113461, 2019). "However, the role of STAT1 during the initiation of inflammation-associated cancer is not clearly understood." (PMID 30235866, 2018). "STAT1 has been associated with therapy resistance in cancer." (PMID 24460726, 2014). "These associations between therapy resistance and STAT1 in cancer may explain the association of STAT1 levels with higher CCL2 and CXCL10 and the apparent lack of therapy sensitivity in high STAT1 patients." (PMID 24460726, 2014). "The reduced levels of STAT1 caused by specific caspase cleavage may have an impact on the immune response and this could also affect cancer development." (PMID 24810717, 2014). "Genome-wide association studies reveal that common disease-associated polymorphisms are enriched in STAT1 promoter binding sites and that deregulated levels and/or activation of STAT1 are closely associated with the development of auto-immune/-inflammatory disorders and cancers." (PMID 24489749, 2014).
cancer (continued). "Additionally, STAT1 belongs to the IFN-related DNA damage resistance signature which is proven to be associated with resistance to chemotherapy across different cancer cell lines." (PMID 22096562, 2011). "STAT1 is overregulated in seven datasets and is related to: 1) angiogenesis; 2) the formation of the macromolecular complex; 3) type I interferon, cytokine-mediated signaling, and pathways in cancer; and 4) Kaposi sarcoma-associated herpes (KSH) and HPV infection." (PMID 39228892, 2024). "Furthermore, STAT1 has also been implicated in the immunosuppression of cancer cells." (PMID 34276757, 2021). "Additionally, the loss of STAT1 has been linked to poor cancer prognosis and metastasis; therefore, we hypothesise that upregulating STAT1 may have a contrary effect." (PMID 34063891, 2021). "In addition, our studies provide proof-of-concept for novel potential strategies for senescence prevention through blockade of ATM-associated DNA damage response and/or inhibition of STAT1/STAT3 signaling in effector T cells for clinical immunotherapy against cancer and chronic infections." (PMID 29339767, 2018). "However, some studies have shown that STAT1 may be linked to tumorigenesis, decreased response to therapy, and overall poorer outcomes for cancer patients." (PMID 29225558, 2017). "Mechanistically, our data support that STAT1 activation is required for the pro-apoptotic effects elicited by CM from apoptotic cancer cell-primed CAFs and by rWISP-1 treatment." (PMID 41522359, 2026). "The dual role of STAT1 in cancer has long been debated, with context-dependent pro- or anti-tumorigenic effects reported across malignancies." (PMID 41522349, 2026). "Here, we found that TREM2+ TAMs were accumulated in GC, promoting PD-L1 expression and CCL8 secretion through STAT1-enhanced transcription, leading to cancer progression and CD8+ T cell exhaustion." (PMID 41253786, 2025). "This study investigates the impact of several clinically used drugs on the expressions of MHC I molecules, including tyrosine kinase inhibitors (TKIs), which enhance MHC I expression through the activation of IFN-γ/STAT1 signaling pathway in cancer cells." (PMID 41019037, 2025). "With prolonged exposure, however, cells acquired resistance, characterized by the sustained activation of ERK, AKT, and STAT1, allowing cancer cells to bypass FGFR1 inhibition." (PMID 41315241, 2025). "Activation of STAT1 via phosphorylation at Tyr701 is well-characterized in cancer biology, facilitating its nuclear translocation and subsequent transcriptional activity." (PMID 41208879, 2025). "We propose that P4HA2 promotes the proliferation and migration of cancer cells by binding to and inhibiting the function of the tumor suppressor protein STAT1." (PMID 40406250, 2025). "Integrated analysis of the GTEx and TCGA databases was conducted to systematically evaluate the transcript expression profiles of STAT1 isoforms across 32 cancer types and 29 normal tissues." (PMID 40849492, 2025). "Correlation analysis revealed that CCL5 correlated significantly with Stat1 in TCGA pan‐cancer data." (PMID 40995650, 2025). "The genes BLK, CDC247, CSK, IRF5, STAT1, STAT4, and TNIP1 are associated with AIDs, and CDC37, DDX6, HSPA6, MAPT, PPIB, STAT1, and STAT4 are associated with cancers." (PMID 40429780, 2025). "In this study, we present the expression profiles of canonical STAT1 isoforms across multiple cancer types and their corresponding normal tissues, and systematically investigate their differential prognostic implications and immunomodulatory mechanisms in OV." (PMID 40849492, 2025). "Alteration of the STAT1 expression can affect the cellular response to stress and inflammation, potentially influencing cancer development." (PMID 40407590, 2025). "The genes BLK, FAM167A, STAT1, STAT4, TNPO3, and TNIP1 are associated with AIDs, and CDC37, DDX6, MAPT, STAT1, STAT4, and UBE3A are associated with cancers." (PMID 40429780, 2025).
cancer (continued). "Since the action of STAT1 varies based on the type of cancer, SP100 tends to guide it toward its growth-limiting role." (PMID 41188771, 2025). "PD-L1 expression in cancer cells is regulated by a variety of transcriptional factors including hypoxia-inducible factor–1α, nuclear factor κB, STAT1, and MYC." (PMID 40779629, 2025). "STAT1, widely recognized as a critical signal transducer and transcription factor, plays complex and context-dependent roles in cancer biology and immune regulation." (PMID 41208879, 2025). "Our study showed that PP2A dephosphorylating STAT1/2 led to the expression downregulation of 5 differential genes, which was conducive to the proliferation and migration of OS cells, and played a pro‐cancer role." (PMID 40956299, 2025). "The dysregulation of both STAT1 and STAT2 has been implicated in various types of cancer, including CRC." (PMID 39868645, 2025). "TAM produce IL‐10 which improves the viability of cancer cells in NSCLC by stimulating the JAK1/STAT1/NF‐κB/Notch1 signaling pathway and promoting the expression of SOX‐2 and other genes linked to cancer cells." (PMID 39927632, 2025). "The interplay between STAT1 signaling and neutrophil polarization toward the N2 phenotype presents a compelling avenue for cancer therapeutic exploration." (PMID 40226609, 2025). "In this context, STAT1 plays a significant role in the migration and invasion mechanisms in various cancer cell types." (PMID 40674249, 2025). "By promoting the transcription of genes involved in NK cell function and upregulating effector molecules, STAT1 helps to amplify the immune response against HER2-positive cancer cells, thereby contributing to the therapeutic efficacy of trastuzumab." (PMID 40650051, 2025). "Overall, the study supports the immunosuppressive role of RNase1 in cancer of negatively regulating STAT1 to impair CD8+ T‐cell cytotoxicity." (PMID 39932384, 2025). "MUC1-C has also been linked to STAT1-mediated activation of the interferon (IFN) type I and II pathways and DNA damage resistance in other types of cancer cells." (PMID 40781226, 2025). "BIN1 also plays a crucial role in inhibiting immune evasion in cancer cells by suppressing the STAT1 and NF-κB pathways, which in turn reduces the expression of the immunoregulatory enzyme IDO." (PMID 40346580, 2025). "It inhibits the proliferation of HCC cells by promoting the STAT1/MTCH1 axis in cancer cells, while also inducing apoptosis and ferroptosis." (PMID 40386780, 2025). "Specifically, genes like PPARD, RPL3, and STAT1, which overlapped in both our epigenomic and transcriptomic analyses, are highly interconnected across AIDs and cancer." (PMID 40429780, 2025). "This STAT1 upregulation not only induces cancer cell dormancy but also drives a self-reinforcing cycle by further increasing type III collagen production." (PMID 40563472, 2025). "Since STAT2 interacted with USP5 after IFN-β treatment and the phosphorylation-deficient STAT2 lost its binding potential, we then knocked out STAT2 in USP5-deficient cancer cells and found that it eliminated the secretion of p-STAT2 and p-STAT1." (PMID 41321309, 2025). "First, does the STAT1-mediated adaptation mechanism we identified operate in other cancer types or with different targeted therapies?" (PMID 41205596, 2025). "IFITM3 and GBP5 both act as downstream factors of the IFN-γ/STAT1 pathway and can serve as cancer biomarkers." (PMID 40909948, 2025). "Using PP2A inhibitor Endothall can abolish the dephosphorylation effect of HCAR1 on STAT1/2, inhibit cancer cell proliferation, migration, and cell cycle, and promote apoptosis." (PMID 40956299, 2025). "Imaging technique reveals STAT1-mediated activation of engineered NK cells, offering a novel method to monitor antitumor activity and enhance the effectiveness of NK cell-based cancer therapies." (PMID 39349746, 2024).